STX10 (syntaxin 10)
Description:
SNARE involved in vesicular transport from the late endosomes to the trans-Golgi network.
Synonyms: Syn10; hsyn10
Tractability: Antibody: UniProt predicts a signal peptide or a membrane-spanning region. PROTAC: ubiquitination databases record sites on it; its protein half-life has been measured.
Gene: Protein-coding gene on chromosome 19 (13,144,058 to 13,150,383, reverse strand). Ensembl gene ENSG00000104915.
Subcellular location: Golgi apparatus membrane
Subcellular location (Human Protein Atlas): Golgi apparatus; Vesicles
Pathways (Reactome):
Vesicle-mediated transport: Retrograde transport at the Trans-Golgi-Network
Gene Ontology:
Molecular function: protein binding; syntaxin binding; SNARE binding; SNAP receptor activity
Biological process: early endosome to Golgi transport; regulation of protein localization; retrograde transport, endosome to Golgi; Golgi vesicle transport; intracellular protein transport; membrane fusion; vesicle-mediated transport
Cellular component: perinuclear region of cytoplasm; trans-Golgi network; vesicle; synaptic vesicle membrane; trans-Golgi network membrane; cytosol; Golgi membrane; membrane
Genetic constraint (gnomAD): Loss-of-function variants: 30 observed, 31.33 expected, observed/expected ratio (o/e) 0.96, 90% interval 0.71 to 1.3. The upper end of that interval is the gene's LOEUF score, 1.3, which puts it in group 5 of 6, group 1 being the genes least tolerant of losing a copy. Missense variants: 340 observed, 325.31 expected, observed/expected ratio (o/e) 1.05, 90% interval 0.96 to 1.14. Synonymous variants: 146 observed, 129.26 expected, observed/expected ratio (o/e) 1.13, 90% interval 0.99 to 1.3.
Homologues: Orthologues: chimpanzee STX10 (99% identical), macaque STX10 (99% identical), pig STX10 (92% identical), dog STX10 (91% identical), rabbit STX10 (81% identical), tropical clawed frog stx10 (55% identical), Drosophila melanogaster Syx6 (45% identical), Caenorhabditis elegans syx-6 (18% identical). Paralogues in human: STX6 (63% identical), STX8 (20% identical).
Diseases named in the same sentence as STX10 in open-access papers:
STX10 is named in the same sentence as 5 diseases in open-access papers, as found by Europe PMC text mining. Sharing a sentence is not in itself a finding about the gene and the disease. The quoted sentences say what the papers report.
viral infection (2 papers, 2021 to 2023). "Indeed, different proteins associated to viral infection like the Long-chain Acyl-CoA synthetase 1 (ACSL1), Calpain-5 (CAPN5) or Syntaxin 10 (STX10), appeared down-regulated in ECFCs after stimulation with the serum of COVID-19 positive individuals." (PMID 37063416, 2023). "In the case of STX10-depleted cells, there was also evidence for reduced glycoprotein expression despite a normal level of DNA replication and expression of the tegument proteins VP22 and VP16, indicating a complex phenotype of virus infection in these cells." (PMID 33975940, 2021).
COVID-19 (1 paper, 2023). A disease caused by infection with severe acute respiratory syndrome coronavirus 2. "The last two, CAPN5 and STX10, were identified by predictive tools as highly discriminating proteins between ECFCs treated with “infected” serums and ECFCs incubated with COVID-19 negative serums (ECFCs+Neg)." (PMID 37063416, 2023).
osteosarcoma (1 paper, 2023). A usually aggressive malignant bone-forming mesenchymal neoplasm, predominantly affecting adolescents and young adults. "Lastly, STX10 was silenced in osteosarcoma cells, which impacted the malignant biological phenotype of osteosarcoma cells." (PMID 37342196, 2023). "Results demonstrated that the mRNA levels of STX10 expression were relatively elevated in MG-63 and 143B osteosarcoma cells." (PMID 37342196, 2023). "The findings suggest that STX10 has the potential to be a new target for osteosarcoma." (PMID 37342196, 2023). "Finally, the cell migration assays and invasion tests have shown that knockdown of the STX10 has hindered the migration and invasion ability of MG-63 and 143B osteosarcoma cells." (PMID 37342196, 2023). "The functional experiment has shown that STX10 may affect osteosarcoma cells’ migration, invasion, and proliferation." (PMID 37342196, 2023). "The qPCR was utilized to analyze the STX10 expression levels in several osteosarcoma cell lines." (PMID 37342196, 2023). "STX10 silence has limited osteosarcoma cell migration, invasion, and proliferation." (PMID 37342196, 2023). "STX10 has been poorly studied in osteosarcoma, and functional tests have yet to be performed." (PMID 37342196, 2023). "Functional tests showed that STX10 knockdown could inhibit the proliferation, migration, and invasion of osteosarcoma cells." (PMID 37342196, 2023). "A comprehensive analysis of GSE36002 databases revealed that STX10 was highly expressed in osteosarcoma tissues compared to normal tissues." (PMID 37342196, 2023).
infection (3 papers, 2015 to 2024). The state of being infected such as from the introduction of a foreign agent such as serum, vaccine, antigenic substance or organism. "In most variants, including Alpha, Beta, Delta, and Omicron BA.1, STX10 showed initial downregulation at 1 hpi followed by upregulation during the early and middle stages of infection." (PMID 39653747, 2024). "However, with the Omicron BA.5 variant, STX10 appeared to be more downregulated as the infection progressed, with its expression decreasing in later stages." (PMID 39653747, 2024). "The syntaxin 10 knockdown was 90.35% of control at 67 h post-infection (~113 h post-transfection), indicating that the slight increase (1.98-fold) in infectious progeny was not due to waning knockdown." (PMID 26442221, 2015). "Further, 30-h inclusions cultivated in syntaxin 10 siRNA-treated cells retained similar amounts of lipids as more immature inclusions formed at 18 h post-infection in untreated HeLa cells." (PMID 26442221, 2015). "To confirm that loss of syntaxin 10 contributed to a delay in the chlamydial developmental cycle, we performed transmission electron microscopy (TEM) at 36 h post-infection in NT and syntaxin 10 siRNA-treated cells." (PMID 26442221, 2015). "We were unable to determine if treatment of infected monolayers with chloramphenicol during early time points of infection inhibits localization of syntaxin 10 or syntaxin 10 positive structures with the inclusion." (PMID 26442221, 2015). "As a first step in understanding the function of syntaxin 10 in chlamydial growth and development, we began by assessing the ability of organisms to produce infectious progeny 24, 44, and 67 h post-infection." (PMID 26442221, 2015). "Further, syntaxin 10 knockdown monolayers, were largely intact at 67 h post-infection, in contrast to the control cells." (PMID 26442221, 2015). "At 24 h post-infection, euo levels are approaching basal levels of transcription, and we found transcript levels increased by only 1.5 fold in organisms grown in syntaxin 10 siRNA-treated cells as compared to organisms grown in NT siRNA-treated cells (data not shown)." (PMID 26442221, 2015). "However, after 44 h of infection (late developmental cycle), there is a statistically and biologically significant ~10-fold decrease in infectious progeny obtained from Chlamydia grown in syntaxin 10 siRNA-treated cells (4.93 × 106 ± 4.85 × 105) vs. control cells (3.75 × 107 ± 1.62 × 106)." (PMID 26442221, 2015). "At 67 h post-infection, 9.78 × 106 ± 1.12 × 106 IFU/ml were recovered from syntaxin 10 siRNA-treated cells." (PMID 26442221, 2015). "Consistent with the organisms being in mid-developmental cycle, at 24 h post-infection, there are no quantifiable differences in Hc1 or OmcB protein levels between organisms cultivated in NT or syntaxin 10 siRNA-treated cells." (PMID 26442221, 2015). "Notably, inhibition of chlamydial protein synthesis at 18 h post-infection by chloramphenicol did not abolish the localization of 3XFLAG-syntaxin 10 to the chlamydial inclusion (last row)." (PMID 26442221, 2015).
cancer (2 papers, 2019 to 2023). A tumor composed of atypical neoplastic, often pleomorphic cells that invade other tissues. "Some of the prominent genes we identified through the networks are DOK5, APP, CTNND1, STX6, STX10, STX16, BACE1, and BACE2; which, agree with the regulation of various cancers based on their co-expression patterns in GeneMANIA." (PMID 37218885, 2023).